VIP (vasoactive intestinal peptide)
Diseases named in the same sentence as VIP in open-access papers (continued):
Sharing a sentence is not in itself a finding about the gene and the disease.
Arthritis (continued). "In vivo VIP treatment in the collagen-induced arthritis model prevents NF-κB nuclear translocation through the inhibition of IκB-α phosphorylation and degradation." (PMID 25101851, 2014). "Our aim was to study serum levels of VIP during the follow-up of an early arthritis (EA) cohort and to analyze its value as a biomarker predicting severity and therapeutic requirements." (PMID 24409325, 2014). "A beneficial effect of VIP on experimental animal models of acute and chronic inflammation, such as acute pancreatitis, septic shock, arthritis, inflammatory bowel disease and lipopolysaccharide (LPS)-induced acute inflammatory, has been demonstrated." (PMID 25101851, 2014). "Vasoactive intestinal peptide (VIP) has been found to act as a potent anti-inflammatory factor in experimental arthritis through regulating the production of both anti- and proinflammatory mediators and promoting Th2-type responses." (PMID 20953422, 2011). "Treatment with vasoactive intestinal peptide (VIP) prevents experimental arthritis in animal models by downregulation of both autoimmune and inflammatory components of the disease." (PMID 16207319, 2005). "However, in early arthritis, we observed that those patients with lower levels had worse prognosis at 2-year follow-up, suggesting that the VIP signaling has a relevant role in the control of the pathology." (PMID 35955723, 2022). "Among them, VIP has been proven to act as a negative regulator of differentiation and resorptive activity of rat and mouse osteoclasts, demonstrating a protective action on bone destruction in experimentally-induced arthritis." (PMID 34944693, 2021). "Moreover, serum VIP levels have been recently identified as a potential prognostic biomarker in early arthritis, as patients with low baseline levels have a poorer clinical course and thus require more intensive treatment." (PMID 34944693, 2021). "Once confirmed that VPAC1 and VPAC2 receptors exhibit a similar expression pattern in osteoclasts derived from healthy donors and early arthritis patients, we next elucidated whether VIP was able to affect the differentiation process." (PMID 34944693, 2021). "In RA, VIP expression has been reported in nerve endings and in other cell types in the inflamed area, and it has been shown to actively modulate immune responses in experimental arthritis." (PMID 31695683, 2019). "Therefore, we decided to perform a multivariable analysis to further elucidate the precise contribution of these SNPs to the evolution of serum VIP levels during the course of arthritis." (PMID 29391448, 2018). "VIP-induced vasomotor control is found to be altered in arthritis." (PMID 27553659, 2016). "In addition, our findings are consistent with those of our previous observation that patients with early arthritis and low VIP serum levels have a more severe disease course." (PMID 25711477, 2015). "Here, we provide strong evidence that collagen-induced arthritis alters intrinsic metabolic capacities of macrophages isolated from rat bone marrow and their reactivity to neurotransmitter stimulation with NA, ACh, and VIP." (PMID 26104678, 2015). "Treatment with VIP reduced the incidence and severity of arthritis in murine models of RA by decreasing the production of proinflammatory cytokines and chemokines, and inducing a shift in the Th phenotype from a Th1-type toward a Th2-type response and generating efficient regulatory T cells." (PMID 24409325, 2014). "Therefore, the objective of this work was to assess VIP levels during the follow-up of patients with early arthritis (EA) and to explore its potential value as a biomarker in RA." (PMID 24409325, 2014). "To test this hypothesis, we established a Freund's complete adjuvant- (FCA-) induced arthritis model in rats and evaluated the effects of EA at Zusanli (ST36), Xuanzhong (GB39) and Shenshu (BL23) on the arthritis and the expression of VIP." (PMID 20953422, 2011).
Arthritis (continued). "When memory Th cells from healthy donors and early arthritis patients are differentiated in Th17 polarizing conditions in the presence of TGFβ, which induces a non-pathogenic profile, the presence of VIP further decreases the pathogenic Th17/1 profile and increases Th17/Treg profile." (PMID 35216459, 2022). "In addition, we studied whether the serum levels of certain key molecules in bone metabolism could be related to baseline serum VIP levels in patients with early arthritis." (PMID 34944693, 2021). "Additionally, we investigated whether there is a relationship between serum levels of VIP and mediators involved in bone remodeling in early arthritis patients." (PMID 34944693, 2021). "In addition, previous researches have shown that VIP could effectively improve the symptoms of arthritis and inhibit cartilage damage." (PMID 29540226, 2018). "The anti-inflammatory and anti-catabolic properties of VIP, which were demonstrated in arthritis before, might offer therapeutic potential in OA, but the ability of VIP to promote hyperalgesia in OA joints needs to be more carefully evaluated in order to consider VIP-targeted therapies in OA." (PMID 28452955, 2017). "Thus, VIP concentrations could predict the outcome of arthritis independently of the treatment prescribed and the phase of the disease." (PMID 24409325, 2014). "Given the modulation of VIP by acupuncture and the importance of VIP in experimental arthritis, we hypothesized that the action of acupuncture on RA may be attributable to the elevation of VIP expression and the subsequent suppression of the arthritis." (PMID 20953422, 2011). "In 2001, Delgado and colleagues described for the first time how VIP treatment of CIA mice improves the progression of the disease, reducing the incidence and severity of arthritis and avoiding joint swelling and destruction of cartilage and bone." (PMID 31695683, 2019). "Furthermore, the intestinal and serum levels of VIP in SIN-treated rats was highly negatively correlated with the histological scores of the joints, the degree of paw swelling, and the arthritis scores, suggesting that VIP might be the key mediator responsible for the anti-arthritic effect of SIN." (PMID 29997506, 2018). "Given that the antagonist of VIP receptor largely diminished the anti-arthritic effect of SIN, it is possible that VIP acts as a message sender between CAP activation and arthritis attenuation." (PMID 29997506, 2018). "In contrast, stimulation with VIP and ACh enhanced proliferation in BMMs from controls, whereas the effect was abrogated in CIA cells at the acute arthritis time point." (PMID 26104678, 2015). "Our objective was to study the mutual influence between senescent Th cells and VIP axis in early arthritis (EA), comparing with non-EA donors." (PMID 33291545, 2020). "Vasoactive Intestinal Peptide (VIP) is a vasoactive neuropeptide, member of the secretin/glucagon family, which possesses different biological functions, including immunomodulatory and anti-inflammatory activity, making it interesting in treatments of immune diseases, including arthritis." (PMID 31049352, 2019). "Furthermore, we found a connection between serum levels of VIP and key regulators of osteoclastogenesis in early arthritis patients that corresponds with its bone-protective effects described in the CIA model, suggesting that VIP may contribute to improving bone homeostasis in these patients." (PMID 34944693, 2021). "As a first approach to test our translational hypothesis, and considering that VIP-induced decrease of the RANKL/OPG has been involved in its protective effect on bone destruction in the CIA model, we analyzed their serum levels in early arthritis patients clustered according to VIP serum levels." (PMID 34944693, 2021).
autoimmune disease (22 papers, 2011 to 2024). A disorder resulting from loss of function or tissue destruction of an organ or multiple organs, arising from humoral or cellular immune responses of the individual to their own tissue constituents. "Previous evidence supports the VIP/receptors axis as a prognostic and diagnostic marker for various inflammatory/autoimmune diseases." (PMID 35955723, 2022). "Reduced serum VIP levels and alterations in VIP receptors/signaling on immune cells have been associated with different inflammatory/autoimmune diseases." (PMID 32747757, 2020). "It has been reported that vasoactive intestinal peptide (VIP) is associated with the downregulation of both inflammatory and autoimmune diseases through regulating T lymphocyte balance." (PMID 31488076, 2019). "Therefore, it is worth speculating that GD might represent an additional autoimmune disease in which a disruption of VIP-mediated immune homeostasis could be linked to clinical outcome." (PMID 32747757, 2020). "Several other molecules are shown to be induced by VIP in allergic and autoimmune diseases, including TSLP, TGF-β, and VCAM-1, all of which are implicated in the pathogenesis of EoE." (PMID 38391908, 2024). "It has been defined that VIP is involved in decelerating the progression of autoimmunity diseases, such as rheumatoid arthritis and osteoarthritis." (PMID 37506142, 2023). "To date, this is the first study to report the relationship between miRNA profiles and VIP and their receptors in autoimmune diseases." (PMID 35955723, 2022). "In the literature, the information provided to date on circulating VIP levels in different inflammatory/autoimmune diseases is variable." (PMID 35955723, 2022). "The VIP axis has clinical utility and has been reported in inflammatory and autoimmune diseases, including IBD." (PMID 36101343, 2022). "VIP is a microenvironment mediator involved in the generation of diversity and plasticity of Th subsets in inflammatory or autoimmune diseases." (PMID 31861827, 2019). "Given the accumulated evidence of VIP anti-inflammatory properties, VIP treatment has been reported to protect against septic shock and various inflammatory and autoimmune diseases, and to act as a survival factor against injury of lung and neuronal cells." (PMID 31861827, 2019). "Here, we consider their role in the pathogenesis of autoimmune diseases and inflammatory disorders and address the potential clinical application of the VIP/receptor axis." (PMID 31861827, 2019). "Here, we discuss the impact of VIP on gastrointestinal function and diseases based on recent findings, also providing insight into its possible therapeutic application to diabetes, autoimmune diseases and cancer." (PMID 31559013, 2019). "Type 1 diabetes and Sjögren’s syndrome (SS) represent other autoimmune diseases in which the beneficial effects of VIP have been shown." (PMID 31861827, 2019). "Vasoactive intestinal peptide is a mediator shared by the neuroendocrine‐immune network, which is considered as a potential candidate for treatment in inflammatory and autoimmune diseases." (PMID 26818776, 2016). "VIP is reported as an anti-inflammatory and immune-modulatory peptide that has considered being a potential candidate for treatment of inflammatory and autoimmune diseases through down-regulation of inflammatory cytokines and mediators." (PMID 27553659, 2016). "Our results provide additional support to in vitro and animal models by reinforcing the role of VIP as a major regulator of the immune system in autoimmune diseases." (PMID 25711477, 2015). "Healing effects of VIP in animal models of inflammatory/autoimmune diseases, including a decrease of Th1 and Th17 profiles, have been reported." (PMID 25430993, 2015). "The VIP and VIP receptors signaling, as an immunomodulatory factor, may play a protective role in the pathogenesis of autoimmune diseases." (PMID 37506142, 2023).
autoimmune disease (continued). "In addition, studies have reported the healing effects of VIP in animal models of inflammatory/autoimmune diseases." (PMID 35614936, 2022). "Moreover, in the last decade, the VIP/receptor axis has emerged as a potential biomarker in autoimmune diseases." (PMID 35955723, 2022). "Furthermore, given the important functions of the VIP axis in the immune system and its involvement in inflammatory and autoimmune diseases, we also aimed to study this axis during the activation of naїve T cells under these in vitro conditions." (PMID 35216459, 2022). "The knowledge generated in animal models and in human ex vivo studies indicated that VIP and its signaling pathways could be used as a therapeutic agent and as a biomarker in inflammatory/autoimmune diseases." (PMID 33291545, 2020). "In this regard, potent anti-inflammatory and immunomodulatory effects of VIP have been demonstrated in several inflammatory/autoimmune diseases, where reduced serum levels of this neuropeptide and alterations in its signalling pathway in immune cells have been described." (PMID 32747757, 2020). "On the 50th anniversary of VIP’s discovery, this review updates our knowledge about the regulatory functions of the VIP/receptors axis in the immune system and presents a spectrum of potential clinical benefits applied to inflammatory and autoimmune diseases." (PMID 31861827, 2019). "The knowledge generated in animal models and in human ex vivo studies related to VIP and its signaling pathways could be translated to clinical reality as two potential tools: as a therapeutic agent and as a biomarker in inflammatory/autoimmune diseases." (PMID 31695683, 2019). "Thus, the VIP axis signaling regulates both the innate and adaptive immune responses in several inflammatory/autoimmune diseases." (PMID 31695683, 2019). "Therefore, our results confirm the VIP-mediated decrease in Th17 and Th1 cytokines reported in several inflammatory/autoimmune disease models." (PMID 25430993, 2015). "From a translational point of view, the VIP axis has an important potential in the control of inflammation and the modulation of several autoimmune diseases, but it could also be used as a biomarker for personalized treatment in autoimmune diseases such as rheumatoid arthritis." (PMID 35216459, 2022). "Therefore, in the present study, we investigated whether VIP might play an important role in the treatment of autoimmune diseases, including LN." (PMID 31488076, 2019). "Therefore, it has emerged as a potential candidate for the treatment of various autoimmune and inflammatory diseases; VIP has also been shown to be effective in the prevention of autoimmune diseases, such as diabetes mellitus, rheumatoid arthritis, EAE, sepsis and inflammatory bowel disease." (PMID 31488076, 2019). "Meanwhile, vasoactive intestinal peptide (VIP) has been reported as a candidate with anti‐inflammatory and immunoregulatory properties for treating autoimmune diseases." (PMID 37506142, 2023). "In this regard, extensive data accumulated from animal models and in vitro human studies have strongly demonstrated the homeostatic effects of VIP on the deregulated expression and signaling of TLR in a context of inflammatory and/or autoimmune disease." (PMID 31861827, 2019). "Furthermore, it would be of particular interest to determine whether the increase in serum VIP levels reported with TNF blockers is class-specific or is also observed in autoimmune disorders treated with other biological therapies, such as blockade of interleukin (IL)-6 or IL-12 signaling." (PMID 25711477, 2015). "In addition, VIP/PACAP, as a regulator involved in inflammation and autoimmune diseases, can directly affect immune cells and regulate Th1/Th2 and Th17/Treg cell imbalances." (PMID 36750876, 2023).
autoimmune disease (continued). "Over the years, the potent anti-inflammatory effects and immunoregulatory capacity of vasoactive intestinal peptide (VIP), mediated by its receptors VPAC1 and VPAC2, have confirmed the potential of the VIP/VPAC axis in the management of various inflammatory and autoimmune disorders." (PMID 35955723, 2022). "In the case of the autoimmune diseases, the ViP/sViP signatures were induced in some, but not others." (PMID 35577777, 2022). "Vasoactive Intestinal Peptide (VIP) and its G protein-coupled receptors (GPCRs), VPAC1, and VPAC2, shape an axis signaling that regulates both the innate and immune response in several inflammatory/autoimmune diseases." (PMID 31695683, 2019). "Furthermore, the anti-inflammatory properties of VIP on Th1 immunity, which is involved in autoimmune diseases including IBD, suggest that VIP is involved in the pathogenesis of IBD and may be a therapeutic target." (PMID 31559013, 2019). "Although variability in the VIP gene has not been reported as a genetic trigger of autoimmune disorders, several findings raise the possibility that once the disease has developed, low expression of VIP could lead to poorer outcome." (PMID 25711477, 2015).
diabetes (22 papers, 2011 to 2025). "Serum VIP was significantly associated with the presence of diabetes mellitus (p = 0.026) and other comorbidities (p = 0.013), and with type of antibiotic therapy (p = 0.019)." (PMID 37146001, 2023). "Additionally, diabetes was associated with a significant reduction in the transcripts of vasodilatory neuropeptides, such as VIP and CALCA, suggesting a mechanism for impaired vascular control." (PMID 40667173, 2025). "In the myenteric plexus of the ileum, diabetes caused a threefold increase in VIP expression." (PMID 37373019, 2023). "Zhizhuwan, a traditional Chinese medicine regulating GI motility, greatly relieved constipation symptoms and decreased VIP level in patients with constipating diabetes mellitus." (PMID 37168808, 2023). "Due to its anti-inflammatory and insulinotropic effects; VIP has been suggested as a potential therapeutic target for treatment of types 1 and 2 diabetes mellitus." (PMID 37146001, 2023). "In the current study, due to disproportionate sample size between the diabetic and nondiabetic patients and the absence of a healthy control group, a firm conclusion regarding the differential role of VIP in CF patients with diabetes cannot be withdrawn." (PMID 37146001, 2023). "A similar increase in the VIP-IR nerve fibers in the vicinity of sweat glands has been demonstrated in skin from rats with 12 weeks of STZ-induced diabetes." (PMID 24847201, 2014). "Independent reports have confirmed increased VIP-IR of nerve varicosities several weeks after STZ-induced diabetes, though studies in human diabetic tissues have not always confirmed these findings." (PMID 25705628, 2014). "With longer durations of diabetes, the numbers of VIP-IR fibers surrounding sweat glands were significantly reduced." (PMID 24847201, 2014). "The role of VIP in diabetes mellitus at molecular level has been reviewed by many researchers." (PMID 37146001, 2023). "Furthermore, in experimental models of diabetes mellitus, diabetic rats had significantly lower gastrointestinal VIP protein levels but higher plasma levels than normal rats, which may indicate that VIP leaks from the gastrointestinal tract to the blood." (PMID 37146001, 2023). "Ga = gastrin, Glu = glucagon, In = insulin, PP = polypeptide, SS = somatostatin, VIP = vasoactive intestinal peptide, DM = diabetes mellitus, RFA = radiofrequency ablation." (PMID 34118524, 2021). "This may lend support to the concept of diabetes in VIP KO mice." (PMID 22103391, 2011). "Altered VIP levels in the ENS structure were found during nerve damage, diabetes, gastric ulcer, and bisphenol A intoxication." (PMID 33353157, 2020). "However, we found that patients with diabetes mellitus had significantly lower VIP levels than patients without the disease." (PMID 37146001, 2023). "Furthermore, NOS/VIP immunoreactivity was reduced (diabetes) or absent (lesion of the cavernous nerve) in penile tissue taken from patients with neurogenic impotence." (PMID 29789007, 2018).